ATP23 (ATP23 metallopeptidase and ATP synthase assembly factor homolog)
Synonyms: KUB3; XRCC6BP1
Tractability: Antibody: its Gene Ontology location is reachable by antibodies, with high confidence; the Human Protein Atlas places it where antibodies can reach. PROTAC: ubiquitination databases record sites on it.
Gene: Protein-coding gene on chromosome 12 (57,906,039 to 57,959,148, forward strand). Ensembl gene ENSG00000166896.
Subcellular location (Human Protein Atlas): Plasma membrane; Vesicles; Cell Junctions; Cytosol
Gene Ontology:
Molecular function: protein binding; DNA-dependent protein kinase activity; metalloendopeptidase activity
Biological process: double-strand break repair via nonhomologous end joining; mitochondrial protein processing; mitochondrial proton-transporting ATP synthase complex assembly
Cellular component: cell junction; cytosol; mitochondrion; plasma membrane; DNA-dependent protein kinase-DNA ligase 4 complex
Genetic constraint (gnomAD): Loss-of-function variants: 20 observed, 25.06 expected, observed/expected ratio (o/e) 0.8, 90% interval 0.56 to 1.16. The upper end of that interval is the gene's LOEUF score, 1.16, which puts it in group 5 of 6, group 1 being the genes least tolerant of losing a copy. Missense variants: 268 observed, 310.03 expected, observed/expected ratio (o/e) 0.86, 90% interval 0.78 to 0.96. Synonymous variants: 94 observed, 106.51 expected, observed/expected ratio (o/e) 0.88, 90% interval 0.75 to 1.05.
Homologues: Orthologues: chimpanzee ATP23 (99% identical), macaque ATP23 (98% identical), pig ATP23 (92% identical), guinea pig ATP23 (87% identical), dog ATP23 (85% identical), mouse Atp23 (80% identical), rat Atp23 (79% identical), tropical clawed frog atp23 (67% identical), zebrafish atp23 (64% identical), rabbit ATP23 (63% identical), Drosophila melanogaster CG5131 (39% identical).
Diseases named in the same sentence as ATP23 in open-access papers:
ATP23 is named in the same sentence as 12 diseases in open-access papers, as found by Europe PMC text mining. Sharing a sentence is not in itself a finding about the gene and the disease. The quoted sentences say what the papers report.
glioblastoma (4 papers, 2013 to 2022). The most malignant astrocytic tumor (WHO grade IV). "For instance, ATP23, a commonly amplified gene within glioblastoma, is involved in NHEJ and is upregulated in response to RT." (PMID 35406779, 2022). "From the 84 DDR genes assessed, the high expression of ATP23, RAD51C and RPA3 was independently associated with poor OS outcomes in the TCGA IDH wild-type glioblastoma cohort." (PMID 35406779, 2022). "At the gene level, the high expression of ATP23, RAD51C and RPA3 independently associated with poor prognosis in glioblastoma patients." (PMID 35406779, 2022).
ATP23 also shares sentences with these, for which no sentence is quoted: tumor (3 papers); glioma (2); anaplastic astrocytoma (1); autoimmune disease (1); cancer (1); cervical cancer (1); colon adenocarcinoma (1); lung carcinoma (1); lupus (1); pilocytic astrocytoma (1); triple-negative breast carcinoma (1).